ADM (adrenomedullin)
Diseases named in the same sentence as ADM in open-access papers (continued):
Sharing a sentence is not in itself a finding about the gene and the disease.
ovarian carcinoma (continued). "In order to evaluate the effects of ADM on the growth of ovarian cancer cell lines, OVCAR-3, OVCAR-EPO10, and A2780 and its paclitaxel-resistant counterparts TC1 and TC3 cells were treated with recombinant human ADM at 1, 10, and 100 nM concentration for 72 hours." (PMID 22859951, 2012). "Apart from this report, no other translational studies addressed the role of ADM in ovarian cancer." (PMID 22859951, 2012).
renal failure (12 papers, 2013 to 2025). "Plasma adrenomedullin concentrations are reportedly elevated in patients with renal failure; however, the underlying mechanism is unclear." (PMID 36139120, 2022). "Background/Objectives: In the context of acute heart failure, proenkephalin A (penKid) has emerged as a prognostic marker for acute kidney injury (AKI), whereas bioactive adrenomedullin (bio-ADM) has been identified as a significant biomarker linked to shock and organ dysfunction." (PMID 40429608, 2025).
atherosclerosis (11 papers, 2013 to 2025). A disease characterized by the build-up of fatty material and calcium deposition in the arterial wall resulting in partial or complete occlusion of the arterial lumen. "It has previously been shown that systemic administration of adrenomedullin or transgenic overexpression of adrenomedullin reduces the progression of atherosclerosis in an ApoE-deficient mouse line." (PMID 33268595, 2020). "Plasma ADM levels are positively correlated to the degree of endothelial damage in atherosclerosis patients, which indicate that it is a good indicator of the prognosis in patients with CA disease." (PMID 36829193, 2023). "Our data identify an antiinflammatory signaling pathway in endothelial cells stimulated by disturbed flow and suggest activation of the endothelial adrenomedullin/CALCRL/Gs system as a promising approach to inhibit progression of atherosclerosis." (PMID 33268595, 2020). "This indicates that modulating the endothelial adrenomedullin/CALCRL/Gs system is a more promising approach to inhibit progression of atherosclerosis." (PMID 33268595, 2020). "High-fat diet induced a significant decrease in plasma H2S levels and atrial natriuretic peptide (ANP) levels in rats with atherosclerosis, and elevated adrenomedullin (ADM) levels." (PMID 30298008, 2018). "Furthermore, ADM production is stimulated by cytokines, growth factors and LPS in vascular smooth muscle cells, suggesting its involvement in endotoxin shock, atherosclerosis and inflammation." (PMID 38714572, 2024). "Levels of ADM have been shown to be higher in patients with atherosclerosis and COPD." (PMID 35263363, 2022). "Plasma ADM levels can reflect the degree of endothelial damage in atherosclerosis patients." (PMID 34956318, 2021). "Plasma levels of ADM also positively correlate with levels of inflammatory markers such as CRP and IL-6, which could explain the relationship between ADM and both atherosclerosis and airflow obstruction/COPD." (PMID 35263363, 2022). "Notably, these correlations might suggest a link between the metabolome and protein markers related to immune signalling (LTα, CD6, CCL21, SELE), energy balance and metabolism-related hormones (IGFBP1, SHGB, ADM, leptin, and STC1), and atherosclerosis/thrombosis inhibitor (PAI1)." (PMID 39154540, 2024). "The fact that mice lacking adrenomedullin, CALCRL, or Gαs in endothelial cells show an increased progression of atherosclerosis indicates that this signaling pathway is constantly activated in areas of disturbed flow." (PMID 33268595, 2020).
melanoma (11 papers, 2014 to 2025). A malignant, usually aggressive tumor composed of atypical, neoplastic melanocytes. "When adrenomedullin levels are reduced or secretion is inhibited, angiogenesis and melanoma growth in vivo are correspondingly inhibited." (PMID 36131942, 2022). "The in vivo study highlights the significance of adrenomedullin as an important factor that promotes melanoma tumor growth and affects the tumor microenvironment by inducing pathologic neoangiogenesis and lymphangiogenesis." (PMID 36497391, 2022). "Adrenomedullin (AM) and AM receptors were immunohistochemically localized in the primitive and metastatic melanoma specimens, suggesting a role of the adrenomedullin system in melanoma growth." (PMID 36497391, 2022). "In vivo, colocalization between CD68+ RAW macrophages and ADM indicates that TAMs are a source of ADM in this melanoma murine model." (PMID 33783686, 2021). "Melanoma conditioned TAMs to produce adrenomedullin (ADM), which in turn mediated angiogenesis by both paracrine (endothelial nitric oxide synthase signaling) and autocrine (M2 polarization of TAMs) effects." (PMID 27886105, 2016). "Targeting the adrenomedullin system may provide a rational basis for future therapeutic modalities in melanoma." (PMID 36497391, 2022). "Additionally, melanoma polarizes immunoregulatory macrophage phenotypes able to secrete adrenomedullin (ADM), a potent and long-lasting vasodilator, as well as upregulates its receptors to promote pro-angiogenic and cancer cell proliferation processes by improving the blood supply to tumor cells." (PMID 38533720, 2024). "However, while loss of adrenomedullin expression in B16-F10 cells did not affect growth of melanoma cells when cultured alone in vitro, it strongly reduced tumor growth in vivo." (PMID 36374225, 2023). "Anti-adrenomedullin-directed antibody and an antagonist of its receptor reduced TAM-induced angiogenesis in vitro and melanoma growth in vivo." (PMID 33171792, 2020). "However, conditioned medium from melanoma cells transduced with shRNA directed against adrenomedullin RNA (Adm-KD-B16) did not increase endothelial proliferation." (PMID 36374225, 2023). "In addition, suppression of adrenomedullin expression in MeWo melanoma cells, but not in HUVECs, led to a strong reduction in adrenomedullin levels in the co-culture." (PMID 36374225, 2023).
pulmonary hypertension (11 papers, 2014 to 2024). Increased pressure within the pulmonary circulation due to lung or heart disorder. "Therefore, when our body lacks sufficient compensatory effect for ADM deficiency, the resistance of pulmonary circulation increases, which might be one of the important aetiological factors for pulmonary hypertension." (PMID 31885565, 2019). "In patients with pulmonary hypertension, elevated levels of ADM are closely correlated with decreased exercise tolerance, the severity of pulmonary hypertension, and a poor prognosis." (PMID 26380264, 2015). "Research into the pathogenesis of HPH has revealed that HIF-1α plays an important role in pulmonary vascular constriction, vascular remodeling and the development of pulmonary hypertension, possibly by regulating the expression levels of ET-1 and ADM at a transcriptional level." (PMID 24944643, 2014).
Insulin resistance (10 papers, 2011 to 2024). Increased resistance towards insulin, that is, diminished effectiveness of insulin in reducing blood glucose levels. "In the previous animal study adrenomedullin deficiency increased oxidative stress and induced insulin resistance." (PMID 33066780, 2020). "The increased ADM release in adipocytes seems to be a compensatory action attempting to restrain insulin homeostasis rather than a causal factor of insulin resistance thus, type 2 diabetes." (PMID 35681200, 2022). "In contrast, high adrenomedullin levels stimulated interleukin-6 and remarkably potentiated stimulatory effects of tumor necrosis factor-α, interleukin-1β and lipopolysaccharide that contribute to the development of insulin resistance." (PMID 33066780, 2020). "However, several animal studies have demonstrated that high endothelin-1 but low adrenomedullin were involved in the development of insulin resistance, suggesting that both vasoactive peptides may be associated with changes in glucose metabolism." (PMID 33066780, 2020). "It has been reported that ADM concentrations in plasma from T2DM patients and amniotic fluid from diabetic pregnancies are elevated compared to uncomplicated pregnancies, suggesting possible involvement of ADM in the pathogenesis of insulin resistance." (PMID 35390031, 2022).
Shock (10 papers, 2007 to 2022). The state in which profound and widespread reduction of effective tissue perfusion leads first to reversible, and then if prolonged, to irreversible cellular injury. "Furthermore, in septic shock, high ADM levels are associated with decreased vascular tone and requirement of vasopressor therapy." (PMID 28050899, 2017). "The midregional fragment of proadrenomedullin (MR-pro-ADM), included between amino acids 45–92, is the most stable part of the ADM, and it has been detected in plasma of patients with septic shock as a consequence of the ADM active peptide degradation." (PMID 24800240, 2014). "The Mid Regional fragment of pro–Adrenomedullin (MR-proADM), included between amino acids 45-92, is the more stable part of the ADM, and it has been detected in plasma of patients with septic shock as a consequence of the ADM active peptide degradation." (PMID 22874067, 2012). "Therefore, we tested the hypothesis whether a newly developed ADM antibody may improve catecholamine responsiveness and attenuate kidney dysfunction in resuscitated, CLP-induced septic shock." (PMID 26266790, 2013).
chronic kidney disease (9 papers, 2011 to 2024). Impairment of the renal function secondary to chronic kidney damage persisting for three or more months. "Pro-ADM and copeptin were significantly higher in older patients and associated with prior chronic kidney disease." (PMID 33413127, 2021). "Adrenomedullin is being pursued as a predictive biomarker for a variety of diseases including cardiovascular mortality and Chronic Kidney Disease (NCT05339009)." (PMID 38107402, 2023). "Ninety-nine patients were excluded due to refusal of study (17 patients), 18 patients had congestive heart failure affecting serum adrenomedullin measurement, 52 patients had chronic kidney disease, and 12 patients had liver cirrhosis." (PMID 36004964, 2022). "MYC is a well-characterized factor contributing to cystogenesis, and ADM is a biomarker for chronic kidney disease." (PMID 31979107, 2020). "Our findings complement and extend previously reported cohort studies of end-stage renal disease for the biomarkers ANP and ADM." (PMID 21408188, 2011). "The protective effects of adrenomedullin in both acute kidney injury (AKI) and chronic kidney disease (CKD) are well documented, underscoring its significant renoprotective properties." (PMID 39200990, 2024).
glioblastoma (9 papers, 2012 to 2026). The most malignant astrocytic tumor (WHO grade IV). "Spatial transcriptomic analysis has identified a subset of tumor-associated macrophages in the hypoxic regions of glioblastomas that compromise tumor vasculature via adrenomedullin secretion." (PMID 40076738, 2025). "According to GSE46531, ADM expression was significantly upregulated in TMZ-resistant glioblastoma stem cell clones." (PMID 36183123, 2022). "According to GSE68029, ADM expression was significantly upregulated in glioblastoma stem cells (GSCs) that survived after 500 μM TMZ treatment compared with untreated GSCs." (PMID 36183123, 2022). "In gliomas, ADM expression levels have been found upregulated, and ADM acts as an effective inducer of the growth of glioblastoma cells." (PMID 36183123, 2022). "In addition, higher expression levels of MMP9, TERT, VEGFA, ZDHHC18, CHEK2, and ADM elevate the probability of predicting glioblastoma." (PMID 40867242, 2025). "Several studies have shown the importance of PAM in the activation of adrenomedullin (ADM), a neuro-peptide involved in angiogenesis and invasion, as well as in reducing the proinflammatory phenotype of microglia, and which occurred to induce tube formation in our glioblastoma cellular model." (PMID 32054826, 2020).
glioma (9 papers, 2014 to 2026). A benign or malignant brain and spinal cord tumor that arises from glial cells (astrocytes, oligodendrocytes, ependymal cells). "ADM has been reported as one of 5 candidate genes associated with glioma resistance to TMZ, which showed to be consistently linked to higher expression of DDIT4 and lower prognosis in TMZ-treated cells." (PMID 36183123, 2022). "Moreover, the high expressed ADM was associated with poor overall survival of glioma patients based on CGGA and TCGA-GBMLGG datasets." (PMID 36183123, 2022). "As glioma grade increased, ADM mRNA expression levels increased and this increase was associated with poorer OS." (PMID 40867242, 2025). "Through RSF and plsRcox algorithms, adrenomedullin (ADM) was eventually obtained as the most significant glycolysis‐related gene for prognostic prediction in glioma." (PMID 38332637, 2024). "Our research findings indicate that the suppression of ADM expression leads to a decrease in glycolysis, migration, invasion, and proliferation of glioma cells." (PMID 38332637, 2024). "In vitro experiments confirmed that IM inhibited glioma cell proliferation, migration, and invasion while also suppressing ADM expression in U373 and U251 cells." (PMID 38332637, 2024). "Comparing with NBTs, both mRNA and protein expression levels of ADM were significantly elevated in glioma tissues." (PMID 38332637, 2024). "Among the four glioma cell lines studied, U251 and U373 cells exhibited the most pronounced upregulation of ADM mRNA levels." (PMID 38332637, 2024). "ADM knockdown was achieved in glioma cells and the specific effects of ADM knockdown on glioma sensitivity to TMZ were investigated." (PMID 36183123, 2022). "Knocking down ADM in glioma cells enhanced the suppressive effects of TMZ on glioma cell viability, promotive effects on cell apoptosis, and inhibitory effects on mitochondrial membrane potential." (PMID 36183123, 2022). "More importantly, under TMZ treatment, inhibition of miR-1297 attenuated TMZ treatment on glioma cells; ADM knockdown partially attenuated the effects of miR-1297 inhibition on TMZ-treated glioma cells." (PMID 36183123, 2022). "Either single ADM knockdown or TMZ treatment notably decreased Ki-67 protein; ADM knockdown enhanced the effect of TMZ in glioma." (PMID 36183123, 2022). "ADM knockdown inhibited, whereas miR-1297 inhibition promoted glioma cell viability; ADM knockdown partially attenuated miR-1297 inhibition effects on cell viability." (PMID 36183123, 2022). "In the present study, ADM expression has been found upregulated in glioma tissues and TMZ- resistant glioma cells based on bioinformatics and experimental analyses." (PMID 36183123, 2022). "In this study, ADM expression has been found upregulated in TMZ -resistant glioma samples, suggesting the underlying effect of ADM on glioma cell TMZ resistance." (PMID 36183123, 2022). "As expected, ADM knockdown in glioma cells amplified the suppression of TMZ on glioma cell viability and promotive effects on cell apoptosis." (PMID 36183123, 2022). "With increasing glioma grade, the mRNA expression levels of ADM were found to be upregulated." (PMID 38332637, 2024). "Similarly, under TMZ treatment, ADM knockdown promoted, whereas miR-1297 inhibition suppressed glioma cell apoptosis; ADM knockdown partially attenuated miR-1297 inhibition effects on glioma cell apoptosis." (PMID 36183123, 2022). "In addition, according to GSE4412 and GSE4290, ADM levels were higher in the high-grade glioma tissue samples." (PMID 36183123, 2022). "Lastly, since miR-1297 targets ADM to inhibit ADM expression, it was investigated that whether miR-1297/ADM axis had a synergistic effect on glioma cell sensitivity to TMZ treatment." (PMID 36183123, 2022). "Thus, searching for miRNAs that might target ADM might be a promising strategy for improving glioma resistance to TMZ." (PMID 36183123, 2022).
glioma (continued). "Overexpression of AM has been observed in various cancers; the oncogenic effects of adrenomedullin (AM) and AM2 (intermedin) in numerous types of cancer, including breast, lung, pancreatic, and prostate cancer and gliomas, have been widely reported." (PMID 41301028, 2025). "Considering that ADM expression is upregulated in glioma tissues and TMZ-resistant glioma cells, ADM knockdown was achieved in LN-229 cells by transfecting short hairpin RNA targeting ADM (sh1-ADM or sh2-ADM); ADM knockdown was confirmed using qRT-PCR." (PMID 36183123, 2022). "Either single ADM knockdown or TMZ treatment significantly decreased tumor sizes, volume and weight; ADM knockdown enhanced the efficacies of TMZ in glioma." (PMID 36183123, 2022). "In this study, single miR-1297 overexpression enhanced TMZ effects on glioma cells, whereas miR-1297 inhibition attenuated TMZ effects; more importantly, ADM knockdown significantly attenuated miR-1297 inhibition effects on TMZ-treated glioma cells." (PMID 36183123, 2022). "Based on univariate and multivariate cox regression analysis, we identified five genes, FABP5, VEGFA, SAA1, ADM, and PRLHR, for prognosis prediction in patients with glioma." (PMID 35800054, 2022). "Additionally, a predictive model based on five HUB genes (FABP5, VEGFA, SAA1, ADM, and PRLHR) was constructed to predict OS in patients with gliomas." (PMID 35800054, 2022). "As for cell viability, single sh1-ADM/sh2-ADM transfection or single TMZ treatment significantly suppressed cell viability compared with sh-NC or non-treatment group; ADM knockdown promoted TMZ inhibition upon the viability of glioma cells." (PMID 36183123, 2022). "Then, ADM expression was determined within a normal human glial cell line SVG p12 and glioma cell lines (U87-MG, A-172, LN-229, and T98G) using qRT-PCR; ADM expression was dramatically increased within glioma cell lines than that within SVG p12 cell line, in particular in LN-229 cells." (PMID 36183123, 2022). "OSM induces ADM (Adrenomedullin) expression in astroglioma cells through induction of signal transducer and activator of transcription-3 (STAT-3) phosphorylation, which is involved in glioma development and progression." (PMID 29168083, 2018). "Amongst the differentially expressed genes, it is interesting to note the over-expression of CALCRL, a G protein-coupled receptor that acts as a receptor for adrenomedullin and calcitonin gene-related peptide (CGRP), and is strongly expressed by in several vascular tumours and types of gliomas." (PMID 25239601, 2014). "Herein, ADM knockdown or TMZ treatment induced caspase 3 and caspase 9 cleavage, as well as mitochondrial membrane potential impairment, suggesting that mitochondrial function might also be involved in ADM knockdown enhancing glioma cell sensitivity to TMZ treatment." (PMID 36183123, 2022).